IL6 (interleukin 6)
Diseases named in the same sentence as IL6 in open-access papers (continued):
Sharing a sentence is not in itself a finding about the gene and the disease.
ovarian carcinoma (continued). "In addition, LPA promotes ovarian cancer growth and metastasis indirectly by stimulating the production of proteases (MMP and urokinase plasminogen activator) and cytokines (IL-6 and IL-8), which play a role in ovarian cancer invasion and metastasis." (PMID 25769037, 2015). "Collectively, among the primary cells in ovarian cancer ascites, CD11b+CD14+ cells, which represent macrophages, induced cell invasion and the proliferation of ovarian cancer cells, at least partly, through the production of IL-6." (PMID 25658637, 2015). "In xenograft models of ovarian cancer, reduced tumor neovascularization, TAM infiltration, and chemokine production were demonstrated after a challenge with siltuximab, a high-affinity anti-IL-6 antibody." (PMID 24901008, 2014). "Furthermore, there is evidence that IL6 and IL8 in particular can exert biological actions that influence ovarian cancer cell growth and migration." (PMID 22410202, 2012). "High pretreatment platelet counts and low pretreatment hemoglobin levels can be negative prognostic factors in patients with ovarian cancer; there was observed the relationship of cystic fluid IL-6 levels with platelet counts and hemoglobin levels." (PMID 22577583, 2012). "These activated BM-MSCs subsequently increase secretion of interleukin-6 (IL-6), interleukin-8 (IL-8), and vascular endothelial growth factor A (VEGFA); promote angiogenesis in endothelial cells; and stimulate the migration of low-invasive ovarian cancer cells." (PMID 40806235, 2025). "Pro-tumorigenic cytokines such as interleukin-6 (IL-6) and interleukin-10 (IL-10) enhance MDSC recruitment and function through activation of the STAT3 signaling pathway, while VEGF and adenosine secreted by ovarian cancer cells further facilitate their accumulation and immune-suppressive effects." (PMID 41301911, 2025). "Finally, we observed that the DEGs DUSP5 (r = 0.487, p < 0.0001), CXCL2 (r = 0.355, p < 0.0001), and IL-6 (r = 0.401, p < 0.0001) were amongst some of the top correlative genes with AREG in the TCGA ovarian cancer cohort, adding a further degree of clinical relevance to our NanoString analysis." (PMID 38831884, 2024). "As a result, IA-0130 most effectively inhibited the proliferation of HEK-Blue IL-6 cells, and surface plasmon resonance analysis confirmed that IA-0130 specifically binds to gp130, not IL-6 or IL-6Rα, and IA-0130 inhibits ovarian cancer cell proliferation, migration, invasion, and tumor growth." (PMID 38916850, 2024). "The epithelial marker β-catenin is also reported to be downregulated similarly in ovarian cancer cells by treatment with TGF-β, but β-catenin was found to be upregulated by IL-8 and nuclear translocation of β-catenin, which is also a form of change expected with EMT as reported in IL-6 treatment." (PMID 36766756, 2023). "EOC patients showed higher levels of proinflammatory cytokines (IL-6, TNF-α, and IL-12), regulatory cytokines (IL-10), and chemokines (CXCL-9 and CXCL-10), which corroborated this environmental proinflammatory/regulatory mechanism for the development of ovarian cancer." (PMID 38141599, 2023). "Additionally, it has been reported that, following IL-6 signaling, phosphorylated STAT3 regulates the nuclear translocation of FoxO3a, leading to increased expression of p27kip1 in T cells, similar to the mechanisms we found in ovarian cancer cells." (PMID 37047012, 2023). "Interestingly, the authors found that metformin cotreatment significantly reduced IL-6 secretion in the cisplatin-stimulated MRC5 fibroblast cell line and fibroblast-facilitated tumor growth when cocultured with the ovarian cancer cell line SKOV3, as well as in murine xenograft models." (PMID 36361682, 2022).
ovarian carcinoma (continued). "Moreover, we further performed a cytokine array analysis, and HM‐macrophages coculture caused a significant increase in many inflammatory cytokines (G‐CSF, GM‐CSF, sICAM1, IL‐α, IL‐1β, IL‐1RA, IL‐6, CCL3, and TNFα), which are known to be abundantly present in ovarian cancer ascites." (PMID 35403834, 2022). "IL-6-producing myeloid-derived suppressor cells (MDSCs), on the other hand, inhibit CD4+ T cell Th1 differentiation, reducing their capacity to assist CD8+ T cells and dendritic cells, resulting in poorer adaptive immunity against the development of ovarian cancer." (PMID 36386196, 2022). "Interestingly, a recent study showed that treatment of ovarian cancer cells with neutralizing IL-6 antibodies resulted in upregulated EGFR, whereas the combination of neutralizing IL-6 antibodies and the EGFR inhibitor gefitinib exhibited enhanced anticancer activity." (PMID 35006432, 2021). "After 21 days of induction with SFTG36 (SCF, FLt-3L, TPO, GM-CSF, IL-3 and IL-6), IS721 (IGF-1, SIS3, IL-7 and IL-21) and IL-15/Hsp70 media, NK cells phenotypes were studied and their cytotoxicity against K562 human erythroleukemia cells and SKOV3 ovarian carcinoma cells was analyzed." (PMID 34098947, 2021). "Furthermore, the immunosuppressive cytokines produced by PRAT, such as IL-10, along with the suppression of IL-6, IL-12p40, and CD86 result in stimulation of ovarian cancer progression, while stimulation of IFNγ, by abrogating IL-12 inhibition, leads to a favorable prognosis in malignant ascites." (PMID 33800984, 2021). "Hence, this study aimed to investigate whether IL-6, IL-8, and TNF-α could be considered as new useful markers for diagnosis of ovarian cancer." (PMID 34573967, 2021). "In addition, IL-6 can induce nuclear translocation and elevate the transcriptional activity of HIF-1α via STAT3 signalling to enhance the chemoresistance against cisplatin of ovarian cancer cells." (PMID 35004308, 2021). "With regards to the M1 markers, our data suggest a slight upregulation of IL-1β, IL-6, and TLR-2 expression in the presence of MSCs and reparixin, despite the fact that gene expression profiles reveal usually an M1/M2 mixed-polarization phenotype in ovarian cancer." (PMID 31504643, 2020). "IL-6-induced STAT3 phosphorylation levels were found to be increased in cells treated with follicle-stimulating hormone (FSH), luteinizing hormone (LH), 17β-estradiol or estrogen and it facilitated cell proliferation in human ovarian surface epithelial (HOSE) and ovarian cancer (OVCA) cell lines." (PMID 31861720, 2019). "Accordingly, in an ovarian carcinoma-bearing mice model, IFN-γ-stimulated M-MDSC increased MHC class II, CD80, and IL-10 expression, and induced CD4+CD25+ Treg in a CTLA-4/CD80-dependent manner, which is in line with our results on IL-10-producing GM-CSF/IL-6 M-MDSC." (PMID 30936876, 2019). "Notably, an increasing amount of evidence has indicated that ovarian cancer cells can polarize TAMs toward the M2 phenotype by upregulating the expressions of leukemia inhibitory factor (LIF), IL-6, and colony stimulating factor-1 (CSF-1), in the intraperitoneal tumor microenvironment." (PMID 30568223, 2019). "Similarly, the evolving ovarian cancer metastatic tumors are metabolically reprogrammed by CAFs through the secretion of C-C Motif Chemokine Ligand 5 (CCL5), C-X-C motif chemokine ligand 10 (CXCL10), and IL-6 to utilize glycogen." (PMID 30380628, 2018). "Additionally, transcriptome-wide mRNA expression analysis of ovarian cancer cells lacking SHMT1 revealed reduced IL-6 and IL-8 mRNA levels." (PMID 28288142, 2017). "Since IL-6/IL-6R signaling is known to act in a number of ways to augment cancer progression, we examined whether the exogenous treatment of IL-6 enhances proliferation, invasion and VEGF-related angiogenesis in ovarian cancer cells." (PMID 25658637, 2015).
ovarian carcinoma (continued). "The pretreatment of anti-IL-6R antibody inhibited those reactions in a dose-dependent manner, indicating that IL-6R is highly expressed in certain types of ovarian cancer cells and that IL-6/IL-6R signaling exerts in a paracrine manner in these cells, even though the cells do not produce IL-6." (PMID 25658637, 2015). "Nieman and colleagues identified that omental adipocytes secrete IL-6, IL-8, chemokine (C-C motif) ligand 2 (CCL2), and tissue inhibitor of metalloproteinases-1, and that mAbs to each of these factors inhibited chemotaxis of ovarian cancer cells toward adipocytes by at least 50%." (PMID 24567915, 2014). "Consequently, we will determine the mechanisms of action involved in ovarian cancer tumor growth, we will measure levels of anandamide and 2-arachidonoyl glycerol as well as protein levels of CB1, CB2, ERα, ERβ, GPER, TNFα, IL-1β and IL-6 in ovarian and tumor tissues." (PMID 35242036, 2022). "In our study, adding medium from cultured tumor cells or IL-6 and VEGF could abrogate the effect of At-EE inhibition of p-STAT3 activation and NF-kB phosphorylation, which demonstrated IL-6, VEGF, and p-STAT3/NF-kB created an autocrine feedback loop in ovarian cancer cells." (PMID 32190078, 2020). "Moreover, patients who responded to chemotherapy tended to have lower ascites IL-6 levels, compared with patients who did not respond to chemotherapy, suggesting that level of IL-6 in the ascites of ovarian cancer patients is an independent predictor of patient’s response to therapy." (PMID 24093089, 2013). "Indeed, raised levels of IL-6 in ascites and serum from ovarian cancer patients correlate with cisplatin and paclitaxel resistance and poor disease prognosis, whereas blockade of STAT3 expression in ovarian cancer cells increases their sensitivity to paclitaxel." (PMID 22481932, 2012). "In our study, miR-320a expression in the intraperitoneal fluid of ovarian cancer patients had a negative correlation with RANTES, TIMP-1, and IL-6." (PMID 37298699, 2023). "This indicates that in NACT-treated ovarian cancer, TNF/IL6 drives the iCAF phenotype rather than IL1B, which has a leading role in promoting the iCAF phenotype in pancreatic cancer." (PMID 35196078, 2022). "HM-1 and ID8 mouse ovarian cancer cells expressed very low levels of VISTA, and the expression did not increase following treatment with IFN-γ, IL-4, IL-6, IL-10, IL-17, or TNF-α." (PMID 30382166, 2019). "In a mouse xenograft model of non-high grade ovarian cancer (IGROV-1 cells), CX-4945 treatment prevented tumor growth, decreased vascular area and proliferative index, and prevented mRNA expression of TNF, IL-6, and VEGF." (PMID 28134850, 2017). "Collectively, exogenous treatment with IL-6 induced proliferation, invasion and VEGF production of ovarian cancer cells, even though they do not express IL-6, and co-treatment with soluble IL-6R was not required." (PMID 25658637, 2015). "While the source of circulating SAA, IL6 and IL8 in ovarian cancer patients is not clear, it has been demonstrated that these proteins are expressed and secreted from ovarian cancer cells." (PMID 22410202, 2012). "In human ovarian cancer SKOV3 cells and the chemoresistant ovarian cancer SKOV3/TR cells, apigenin significantly decreased Axl and Tyro3 receptor tyrosine kinase at both RNA and protein levels, without changing the IL-6 production and phospho-STAT3 protein levels." (PMID 29034071, 2017). "Moreover, we show that IL-6, but not IL-8, is one of the major cytokines in CAF-CM that contributes to HK2 up-regulation through binding of IL-6R in ovarian cancer cells, suggesting that HK2 expression can be regulated by the tumor microenvironment in ovarian cancer." (PMID 31212816, 2019).
anemia (513 papers, 2004 to 2026). A reduction in the number of red blood cells, the amount of hemoglobin, and/or the volume of packed red blood cells. "Here, we infer that strain-directed immunomodulation contributes to differences in anemia severity, with pro-inflammatory cytokines IL-1β, IL-6, IFN-γ, and TNF-α implicated." (PMID 41602558, 2026). "A cross-sectional study indicated that low hematocrit, decreased hemoglobin levels—as in anemia—and increased IL-6 were associated with a greater likelihood of sarcopenia." (PMID 40507694, 2025). "Overexpression of IL-6 in chronic inflammatory diseases and malignancies has been associated with anemia and cachexia." (PMID 41010767, 2025). "A study indicates that inflammatory markers like C-reactive protein (CRP) and interleukin-6 (IL-6) are elevated in frail individuals and linked to anemia and poor health outcomes." (PMID 40337739, 2025). "Cancer-associated anemia is thought to be partially mediated via an increase in inflammatory cytokines, like interleukin 6 or tumor necrosis factor alpha, that are believed to negatively interfere with iron metabolism." (PMID 40867262, 2025). "In comprehensive analyses of long-term anemia, higher IL-6 levels and high baseline β2-microglobulin levels are independent risk factors for prolonged anemia, while high baseline hemoglobin is an independent protective factor." (PMID 39253080, 2024). "We assume that sRANKL, like sRAGE, reflects iron deficiency, caused by increased IL-6 and prohepcidin (hepcidin precursor) in anemia of the chronic inflammatory process." (PMID 39684440, 2024). "Proinflammatory cytokines, especially interleukin‐6 (IL‐6), high iron stores, and infections induce hepcidin synthesis whereas low iron stores, anemia, and hypoxia are linked to suppressor effects." (PMID 39055215, 2024). "IL-6 has also been reported to be significantly associated with anemia in RCC and induce hypercalcemia." (PMID 38658967, 2024). "According to a prior study, interleukin-6 levels increased with age and were associated with anemia in elderly individuals." (PMID 39055698, 2024). "The production of pro-inflammatory cytokines, primarily IL-6, by immune cells and tumor cells is a significant factor in the etiopathogenesis of anemia linked to cancer." (PMID 38337488, 2024). "TA is often associated with anemia, particularly during the active inflammatory stage, when IL-6 induces the production of hepcidin, an acute-phase reactant, leading to the inhibition of iron absorption, manifesting as anemia." (PMID 39600747, 2024). "Further, elevated IL-6 levels have also been associated with the severity of anemia in humans infected with P. vivax and P. falciparum." (PMID 36839438, 2023). "Another study also suggested that the serum hepcidin levels were associated with the IL-6 and IL-10 levels in anti-inflammatory processes and determined the anemia status of patients." (PMID 36668942, 2023). "IL-6 is a pleiotropic cytokine that is involved in the occurrence of systemic manifestations, such as inflammation-associated anemia." (PMID 37074208, 2023). "While IL-6 is of significance in the pathology of anaemia, iron deficiency and anaemia of inflammation are of moderate public health concerns in the Mount Cameroon area." (PMID 37507740, 2023). "In SLE patients, we demonstrated an association between elevated serum IL-6 levels and the occurrence of anemia." (PMID 37371554, 2023). "Oncology studies and studies evaluating the effects of recombinant human IL-6 support a causal link between IL-6 production and the development of anemia in patients with chronic disease, contributing to inflammatory conditions in chronic-diseased tissues." (PMID 36986536, 2023). "Liver hepcidin 1 mRNA levels, a downstream mediator of IL-6 involved in inflammation-associated anemia, were decreased in IL-18BP KO as compared with WT mice." (PMID 37074208, 2023).
anemia (continued). "In patients with renal cell carcinoma, IL-6 levels greater than 10 pg/mL were associated with a marked increase in the risk of anemia." (PMID 37208766, 2023). "Recently, we described that anemia of chronic TB disease was associated with more severe clinical disease and elevated levels of pro-inflammatory IL-6 but a suppressed IFN-γ response." (PMID 38162636, 2023). "Elevated IL6 levels intensifies RT-induced anemia by upregulating hepcidin causing functional iron deficiency." (PMID 35672745, 2022). "Expression of hepcidin is upregulated by iron loading and inflammatory cytokines (especially interleukin 6) and downregulated by iron deficiency, hypoxia, anemia, and erythroferrone produced by erythroid cells." (PMID 35790696, 2022). "Low body mass index (BMI), HIV infection, helminthic co-infection, low selenium concentrations, old age, high retroviral load, high IL-6 concentrations, and female gender are some of the risk factors associated with anemia in adults with TB." (PMID 36106202, 2022). "Dysregulated production of hepcidin has been linked to anemia and inflammation, and IL‐6 is a major inducer of hepcidin production." (PMID 34762752, 2022). "Proinflammatory cytokines, including tumor necrosis factor (TNF)-alpha, interleukin (IL)-1, IL-6, and IL-10, play important roles in RA-associated anemia." (PMID 36008838, 2022). "IL-6 induces hepcidin which plays a critical role in the development of anemia by causing alterations in iron homeostasis." (PMID 36008838, 2022). "Paracrine effects of IL-6 suppressed erythroid differentiation and caused anemia in animals; a neutralizing IL-6 antibody reversed this effect in vitro and in vivo." (PMID 33711076, 2021). "When multivariate analysis was performed, the variables independently associated with an increase in IL-6 were anemia and renal dysfunction." (PMID 33535417, 2021). "Chronic inflammation has also been associated with aging, characterized by anemia, immunosenescense, and thrombocytosis, as well as overproduction of inflammatory cytokines IL-1, TNFα, and IL-6." (PMID 34502021, 2021). "In our population, anemia in older Mexican adults has an inflammatory component, characterized by higher hepcidin and IL-6 levels in AI and CKD, while in UEA an association was revealed with IL-6." (PMID 34836070, 2021). "Among offspring of iron-deficient women, the odds of fetal anemia increased with fetal α+-thalassemia, as well as these patterns of cord blood cytokines: increased cord IL-6, decreased TNF-RI, and decreased sTfR." (PMID 33995348, 2021). "The factors independently associated with the increase in IL-6 were anemia 3.513 (1.163–10.607); p = 0.026 and GFR CKD EPI 0.963(0.936–0.991); p = 0.009." (PMID 33535417, 2021). "IL-6 induces hepcidin and causes secondary anemia, promoting CRP production and inhibiting albumin production." (PMID 34117557, 2021). "Interleukin-6 (IL-6)-producing pheochromocytomas reportedly cause high inflammatory states and induce coagulopathy and anemia." (PMID 34117557, 2021). "Childhood anemia also increases the susceptibility of children towards infection by its effects on defective Interleukin-2 (IL-2) and Interleukin-6 (IL-6) production and thus compromises immunity." (PMID 34521396, 2021). "Among all parity groups, fetal anemia risk was higher in newborns with thalassemia, higher cord levels of IL-6, and lower cord levels of TNF-RI and sTfR." (PMID 33995348, 2021). "Patients with elevated interleukin-6 seem to have a special phenotype with a greater association with cardiorenal syndrome and anemia, both important comorbid conditions associated with heart failure." (PMID 33535417, 2021). "Higher levels of TNFRII and IL-6 increased the risk of fetal anemia, whereas higher levels of TNF-RI and sTfR decreased the risk." (PMID 33995348, 2021). "In studies of SLE in adults, IL-6 was found to be associated with anaemia in those with lupus nephritis." (PMID 33882880, 2021).